FN1 (fibronectin 1)
Diseases named in the same sentence as FN1 in open-access papers (continued):
Sharing a sentence is not in itself a finding about the gene and the disease.
tumor (continued). "FN1 is an established marker for epithelial-mesenchymal transition (EMT), and stimulated FN1 expression has been observed in various types of cancer and is associated with enhanced cell migration, invasion and tumor metastasis." (PMID 34758823, 2021). "In short, tumor-stromal remodeling genes FN1 and SPP1 were highly expressed in male-derived TAMs." (PMID 34804043, 2021). "Furthermore, FN1 is a glycoprotein of the extracellular matrix, which enables interactions between tumor cells and the extracellular matrix and plays essential roles in cell adhesion and dissemination processes." (PMID 34680330, 2021). "FN1 deposits could be detected in vessels of human metastatic livers and represent the substrate for circulating tumor cells to adhere to endothelial cells, to extravasate and form metastasis." (PMID 33731188, 2021). "Furthermore, our analysis show that immune infiltration levels and immune markers are correlated with FN1 expression level in THCA, suggesting a potential role of FN1 in tumor immunology and its possible used as a cancer biomarker." (PMID 35141255, 2021). "High expression levels of FN1 are associated with a poorer prognosis in THCA, indicating that FN1 expression could be used to predict tumor patient' prognosis." (PMID 35141255, 2021). "In non-tumor-bearing mice, lung tissue from obese mice demonstrated increased collagen deposition, which may be due to elevated expression of Lox and Fn1 by lung stromal cells." (PMID 33670906, 2021). "In our ceRNA network analysis, FN1 was found to directly interact with C3 and be regulated by miR-127, miR-216b, and miR-429, which have been reported to be downregulated in various tumors and act as tumor suppressors in RCC." (PMID 34688260, 2021). "Moreover, up-regulation of FN1 spurred the reversal of anti-tumor effects of hsa_circ_0081534 knockdown upon NPC cells progression." (PMID 33082297, 2020). "However, tumours that eventually started growing contained abundant αSMA‐positive CAFs correlating with increased host Fn1 expression." (PMID 32145051, 2020). "Interestingly, most deregulated genes, such as IL6, RelB, RelA, Plac8, ITGA5, CXCL12 and FN1, among other cytokines and growth factors, have been involved in tumor growth and progression." (PMID 32848147, 2020). "Moreover, a multivariate analysis showed that low FN1 expression in tumor specimens was an independent predictor of poor prognosis." (PMID 33112827, 2020). "LTBP1 and FN1 had different expression patterns in tumor cells and fibroblasts." (PMID 32216815, 2020). "However, murine Fn1 expression was elevated in 501mel tumours, and this correlated with an abundance of cells positive for the cancer‐associated fibroblast (CAF) marker αSMA." (PMID 32145051, 2020). "Furthermore, clinically relevant genes that are associated with tumor growth such as VIM, ITGB1, FOXQ1, FN1, MSN, CXCL and TMPRSS4 were also downregulated." (PMID 32784836, 2020). "Submitting our gene list to the MSigDB identified gene sets characteristic of an invasive phenotype in tumours of high FN1/CCND1 expression, including upregulation of gene sets related to extracellular matrix, cell movement, cancer-specific invasion and mesenchymal phenotype." (PMID 32037399, 2020). "Finally, the fibronectin 1 (FN1) gene is an extracellular matrix glycoprotein that is involved in cell proliferation under homeostatic conditions but promotes metastasis of tumor cells when its expression is modulated." (PMID 33112566, 2020). "The localization of FN1 in the endothelium could potentially contribute to its role in angiogenesis that is depicted in tumor pathogenesis." (PMID 33029756, 2020). "Based on our findings, we speculate that the expression of RUNX2 in GC tissue changes with the degree of tumor malignancy, and its effect on FN1 also changes, and with a high degree of malignancy, the two genes are negatively correlated." (PMID 33313404, 2020).
tumor (continued). "We previously identified CTCs to have increased FN1 expression as compared to primary tumor cells." (PMID 32630254, 2020). "To investigate whether ALDH3A1 expression might be involved in mesenchymal phenotype development, we studied EMT markers (CDH1, Zeb1, VIM, and FN1) at the mRNA expression level in all stem-cell-like tumor cells." (PMID 31817719, 2019). "In murine models of melanoma and prostate cancer, IFN-γ production by NK cells triggered by NKp46 activation was found to induce expression of the extracellular matrix protein fibronectin 1 in tumor cells, altering tumor architecture and controlling metastatic invasion." (PMID 30984204, 2019). "Abrogating FN1-integrin interactions have produced strikingly positive pre-clinical results in various animal models of cancer by impeding angiogenesis and inhibiting tumor growth." (PMID 30736807, 2019). "In this study, COL1A1 and FN1 were all ECM genes with elevated mRNA levels in tumor stromal cells." (PMID 30237810, 2018). "Furthermore, the tumor sections were stained for E-cadherin, FN1, ZEB1 and vimentin expression to quantitatively evaluate the EMT associated marker." (PMID 30098599, 2018). "Interestingly, HBV integration in the FN1 gene seems to be specific to adjacent non-tumour liver tissue and results in recurrent HBV-FN1 fusion transcripts." (PMID 30037029, 2018). "As more invasive cells express more ITGA5 on their surface and secrete EVs with more ITGB1, the role of FN1-α5β1 in the GBM tumour microenvironment should be further delineated as it may offer an attractive therapeutic target." (PMID 27770278, 2017). "Moreover, the mesenchymal markers FN1 is up-regulated in tumor buds compared to the regular cancer cells, and down-regulated in the stroma of tumor buddings compared to the stroma of regular cancer cells." (PMID 28687755, 2017). "Fibronectin 1(FN1), predominantly expressed in various malignancies but not in normal tissues, was mainly involved in this pathway and a specific tumor regimen for the FN1 gene could be implemented." (PMID 29050278, 2017). "Notably, COL1A1 and FN1 are among the most highly expressed genes in the activated stroma subtype, suggesting tumor-promoting roles of activated CAFs." (PMID 27528027, 2016). "We further examined whether blocking FN1/SPP1-ITGAV signaling could inhibit the outgrowth of tumor cells in fibrotic lungs." (PMID 27329720, 2016). "Collectively, we suggest that fibrotic microenvironment may enhance the metastatic seeding of tumor cells in the lung by chemoattracting tumor cells and inhibiting their apoptosis via activating the FN1/SPP1-ITGAV signaling." (PMID 27329720, 2016). "In addition to FN1 and SPARC, other well-established EMT-associated genes are also upregulated in these tumor samples following letrozole treatment including TWIST1, SNAI2, ZEB1, and ZEB2." (PMID 24944582, 2014). "A number of tumor-associated or epithelial-specific genes are used in the detection of CTCs of different types of cancer, including CK, Her2, CEA, MUC1, EpCAM, EGFR, hTERT, survivin, c-met, FN1 and several other mRNA markers." (PMID 23599802, 2013). "In addition, new therapeutic strategies targeting the ECM components are being evaluated, such as specific molecules inhibiting the interaction between FN1 and tumour cells or therapeutic agents conjugated to antibodies specific for tumour environment." (PMID 24499539, 2013). "This might suggest that, for FN1 integration event, the effects on the FN1 might be position dependent or context (tumor vs. adjacent normal) dependent." (PMID 23236287, 2012). "None of the 15 known or supposed markers for CTC detection was considered for further investigations either due to detectable expression levels (ERBB2, ESR1, SERPINE1, SERPINE2 and FN1) in healthy controls or due to inadequate gene expression in the tumor cell lines." (PMID 21129172, 2010).
tumor (continued). "NCBI Entrez gene database reported that: CHEK2 is a cell cycle checkpoint regulator and putative tumor suppressor, and associated with GBM; GSTM5 was reported to be involved in cancer, BCL11A is a proto-oncogene, and FN1 is involved in tumor metastasis and angiogenesis." (PMID 21114830, 2010). "Additionally we selected seven other genes, ATF3, ADAMTS1, EGFR, PRNP, IGFBP6, ID4 and FN1, found to be differentially expressed according to tumor subtype and ER+/ER- classification from the tumor-specific differentially expressed gene-set." (PMID 19116033, 2008). "In addition, we found that fibroblasts, as signal senders, may cooperate with TREM1+ PMN-MDSCs in extracellular matrix remodeling and tumor progression by secreting collagen and FN1 to interact with the CD44." (PMID 41413734, 2025). "The role of FN1 in tissue stem cells with high communication intensity may facilitate interactions with other cells in the tumour microenvironment by supporting tumour cell attachment and spread, suggesting that XBP1, TRPC6 and TTC28 may influence the tumour microenvironment." (PMID 40046334, 2025). "Notably, IFN-γ inhibits tumor metastasis mediated by overexpression of fibronectin-1." (PMID 39768997, 2024). "It’s noteworthy that, as a cell adhesion molecule, alterations in FN1 expression were frequently manifested in tumor cells, and thus we hypothesized that the lack of FN1 expression might be related with the poor cohesion of tumor cells." (PMID 38898490, 2024). "In addition to Col1 and FN1, we observed a reduction of HA, a high-molecular weight, unbranched, nonsulfated glycosaminoglycan that is an important structural component of various tissues including the tumor ECM." (PMID 37389973, 2023). "Furthermore, a protein–protein interaction analysis obtained from the STRING website showed a direct interaction between SPP1 and CD44, MMP3, MMP7, TIMP1 and fibronectin-1, all of which are directly involved in the extracellular matrix remodeling and promotion of tumor metastasis." (PMID 38067407, 2023). "Meanwhile, the expression of MYH9, FN1, LTBP1, CALR and AKAP12 is effective in discriminating HR-NB from LR-NB patients, indicating that these non-invasive biomarkers may be used to detect patients at risk of developing aggressive tumor phenotypes." (PMID 37947594, 2023). "Therefore, we hypothesized that FN1 in tumor cells may be a key macrophage-regulated ECM gene that promoted enzalutamide resistance in bone-metastatic PC." (PMID 36749798, 2023). "Therefore, FN1/ITGB1 may be a potential therapeutic target to target the tumor microenvironment in PTC." (PMID 37733241, 2023). "Activating the FN1 signaling may enhance the metastatic seeding of tumor cells in the lung." (PMID 37656377, 2023). "The Mon Fn1 cell population is characterized by inflammatory features, including increased expression of the chemokine receptors Ccr2 and Ccr1 facilitating cell recruitment, immune suppression and tumor-promoting factors such as galectins (Lgals3/9), and the NLRP3 inflammasome inhibitor Tmem176b." (PMID 37756565, 2023). "Signaling networks such as VCAM, WNT, FN1, etc., known to be associated with dormancy escape were enriched in the DTX-treated tumor tissue, while BMP and FGF signaling networks, which are known to play a role in cancer dormancy, were enriched in VEH-treated dormant/control tumor tissue." (PMID 37699010, 2023). "Moreover, our data weakly indicates that an overall higher FN1 expression in an ALK-driven tumor tissue could be correlated with worse survival." (PMID 37511126, 2023).
tumor (continued). "In addition, tumor-specific MFAP5 + fibroblasts could also secrete FN1 and TGF-β to interact with certain receptors of myeloid cells to promote tumor progression." (PMID 37344903, 2023). "Additionally, the expression of TWIST1, SNAI1, FN1, and CDH2 also showed significant association with NUTF2, suggesting that NUTF2 may play a major tumor-promoting role in the Lumina A BRCA subtype." (PMID 35155261, 2022). "NK cells might limit tumor metastasis by activating NKp46 in the intratumoral NK cells secreting interferon-gamma, and interferon-gamma increases the expression of extracellular matrix protein fibronectin 1, affecting the primary tumor architecture." (PMID 36359863, 2022). "In addition, β1 integrins and tumor adhesion to FN1 mediate resistance to radiotherapy." (PMID 36076905, 2022). "Notably, the data of both ICC and CHC indicated a recurrently integrated genes FN1 in non-tumor tissue, which was consistent with previous research on HCC, suggesting that the adjacent non-tumor tissues of all three PLC types had the analogous profile of HBV integration." (PMID 36123506, 2022). "Importantly, using qRT-PCR, we could validate the higher mRNA expression of the selected genes based our bioinformatics analysis; most selected genes, except SPP1 and FN1, were upregulated in tumor tissue." (PMID 34126961, 2021). "In conclusion, our data indicate that FN1 is degraded by the p62-dependent autophagy–lysosome pathway, independent of the ubiquitin–proteasome pathway, and indicate that FN1 is a potential prognostic biomarker for HNSCC because it has a strong association with EMT and tumour invasion and metastasis." (PMID 33318468, 2020). "Therefore, we hypothesize that hsa_circ_0081534 might have exerted its tumor oncogenic effects through regulating the miR-508-5p/FN1 axis in NPC." (PMID 33082297, 2020). "Poor survival may be alternatively related to a role of FN1 in the tumor microenvironment." (PMID 32411604, 2020). "Furthermore, studies have shown that FN1 is involved in tumor invasion and metastasis." (PMID 33313404, 2020). "Similarly, ALDH3A1 is associated with the overexpression of NFkB and EMT markers such as VIM, FN1, and Zeb1, revealing that the enzyme, through a direct effect on the redox state of tumor cell metabolism, is involved in the process that links stemness, EMT, and inflammation in tumor cells." (PMID 31817719, 2019). "We demonstrated that treatment strategies containing metformin significantly reduced tumor growth and metastasis in nude mice, and that metformin caused an increase in AMPK and PTEN activity and suppression of mTOR/p70S6K/S6, as well as invasion/migration-associated genes, e.g., MMP7, DCN and FN1." (PMID 25909163, 2015). "Therefore, we hypothesize that the FN1, CTSD, and GSN interaction is associated with cell adhesion and metastasis in tumor cells." (PMID 26056562, 2015). "Compared to the intercellular interactions in normal tissues, we noted several tumor-promoting signaling pathways specificly found in PCa tissues, including ANGPTL, FN1, GDF, CSF, PTN, and LAMININ signaling pathways." (PMID 40438108, 2025). "Our study also introduces a RS that integrates patient demographics, tumour characteristics, and key gene expressions such as FN1, VASP, and CEP63 to predict tumour relapse in MIBC patients undergoing NAC." (PMID 40149716, 2025). "Macrophage- and fibroblast-derived fibronectin 1 (FN1) can activate the Hippo pathway via JUN, promoting tumor metastasis." (PMID 40055311, 2025). "As a result, we observed that FN1 expression in α‐SMA+ stroma had a statistically significant positive correlation with both myeloid cell and T cell levels in tumor AOIs from ROIs with rich α‐SMA+ stromal cell presence." (PMID 39245631, 2025). "All four candidate genes (THBS2, FN1, COL1A1, COL5A1) were found to be upregulated in tumour samples compared to matched normal samples in our microarray analysis." (PMID 40860666, 2025).
tumor (continued). "While immune inhibitory genes are often upregulated in tumors to suppress anti-tumor immunity, their concurrent downregulation with KDM6A and FN1 suggests an alternative mechanism of immune escape, possibly creating a less immunogenic microenvironment." (PMID 39833941, 2025). "CONCERT shifted the NEX profile of the central Tgfbr2-KO patch toward that of the actual tumor-periphery niche: for Fn1, mean NEX decreased from 3.917 to 3.228, approaching the observed value in tumor periphery (2.625)." (PMID 41292874, 2025). "Across all three tumor grades, we observed upregulation of two factors: TGFB1 (TGF‐β) and FN1 (fibronectin) in α‐SMA+ stroma AOIs when compared to all other tissue type AOIs." (PMID 39245631, 2025). "This discovery expands FN1’s traditional role from a “passive ECM component” to an “active immune regulatory factor,” revealing its crucial role in shaping the “cold tumor” microenvironment." (PMID 40678072, 2025). "To summarize, the presented tumor is a CCMNs with involvement of the TMJ region and FN1::FGFR2 fusion." (PMID 39404883, 2025). "Studies have reported that FN1 can stimulate the proliferation of growth-arrested mammary epithelial cells, induce EMT response, disrupt the cavitary acinar structure, and promote tumor-like behavior." (PMID 41368570, 2025). "CSR‐related genes (COL1A1, LOXL2, LUM, FN1, and TGFB1) reflect extracellular matrix deposition and stromal activation, hallmarks of invasive tumor behavior." (PMID 41407509, 2025). "Specifically, FN1 (Log2 FC = 6.2), UGT1A1 (Log2 FC = 6.1), AGT (Log2 FC = 3.31), and COMT (Log2 FC = 2.4) were significantly upregulated in tumor tissues compared to normal tissues." (PMID 40564071, 2025). "The cell-type-specific (defined based on marker gene expression profiles and clustering analysis) expression of CD44, FGF2, FGF10, KDM6A, FN1, and MMP2 in the tumor microenvironment of UCEC was analyzed using the TISCH2 database." (PMID 39833941, 2025). "The fibronectin 1(FN1) derived from HCC cells regulates the glycolytic metabolism of macrophages, which in turn affects their anti-tumor properties and the expression of PD-L1 mediated by inflammation." (PMID 39897050, 2025). "Among the upregulated proteins, we observed significant elevation of extracellular matrix proteins, including FN1 (Fibronectin 1) and THBS1 (Thrombospondin 1), which are established mediators of tumor invasion and metastasis." (PMID 40861812, 2025). "This relationship is well-acknowledged; myofibroblasts in the tumour-adjacent tissue increase the deposition and crosslinking of ECM components (e.g. COL, FN1), impairing patient outcomes." (PMID 40792276, 2025). "The identification of gene co-expression modules containing classical EMT markers (e.g., VIM, ZEB1, SNAI2) alongside ECM-related genes (COL1A1, FN1, SPARC, LOX) underscores a tightly coordinated interaction driving tumor cell plasticity and invasion." (PMID 40943497, 2025). "Low and high neoplastic are in multiple tumor malignant progression-related pathways such as MIF, ITGB2, and FN1 with different cells for messaging." (PMID 40303412, 2025). "Pathway-level breakdown revealed that CaWP cells exhibited enhanced outgoing signaling via COLLAGEN, FN1, LAMININ, and CD44 axes—key mediators of extracellular matrix organization and tumor–stroma interaction." (PMID 41561767, 2025). "The neoplasm showed high expression levels of LGR5 (stem cell marker gene, investigated as a therapeutic target in CRC), FN1 (extracellular matrix remodeling), and TGFBR2 (conditional tumor suppressor/activator as part of TGF signaling)." (PMID 40667282, 2025). "Among the key regulators of the TME, fibronectin 1 (FN1), a major extracellular matrix (ECM) protein, has emerged as a critical modulator of tumor-immune interactions." (PMID 40380260, 2025).